MIR8056 (microRNA 8056)
Synonyms: hsa-mir-8056
Gene: MicroRNA gene on chromosome 5 (173,347,455 to 173,347,536, forward strand). Ensembl gene ENSG00000274994.
Homologues: Orthologues: chimpanzee MIR8056 (100% identical).